RB1 (RB transcriptional corepressor 1)
Diseases named in the same sentence as RB1 in open-access papers (continued):
Sharing a sentence is not in itself a finding about the gene and the disease.
tumor (continued). "Consistent with a role for Rb1 in suppressing adipogenesis, homozygous Rb1 co-deletion dramatically shifted the tumor spectrum towards fatty tumors and reduced incidence of OS." (PMID 26317218, 2015). "RB1 is a tumor suppressor, but is also an established inhibitor of oxidative metabolism in both white and brown adipose tissue." (PMID 25996876, 2015). "In this model, Rb1 is a major barrier to tumor initiation, and it is inactivated by cdk hyperphosphorylation in these tumors." (PMID 25880398, 2015). "Analysis of MLS/RCLS derived cell lines showed RB1 protein expression in level with other tumor cell lines and much stronger than the expression in cultured normal fibroblasts." (PMID 25093008, 2014). "One of the tumors had a wild type RB1 gene and expressed nuclear RB1 protein in virtually all the tumor cells." (PMID 24509483, 2014). "As both Rb1 and p16 are tumor suppressor genes, alterations in one or both proteins disrupt the cellular mechanisms available to halt tumor proliferation." (PMID 24752337, 2014). "RB1 is a well-known tumor suppressor with an important role in controlling the cell cycle, that is frequently inactivated in many human cancers." (PMID 24722523, 2014). "In virus positive tumors, LT-Ag is thought to inhibit survivin expression via sequestration of the RB1 tumor suppressor, and RNA silencing of LT-Ag was able to restore susceptibility to miR-203 overexpression." (PMID 25329450, 2014). "The tumor inhibition rates revealed a marked effect of PNS, Rg1, Rb1, or R1 on inhibiting tumor growth in the complex model." (PMID 24903055, 2014). "Our IHC analysis showed only weak signals for the RB1 protein in MLS tissues compared to control tissue samples from other tumor types." (PMID 25093008, 2014). "In one of the tumors, the RB1 gene was unaltered, the MYCN gene was amplified and RB1 protein was expressed in the nuclei of the tumor cells." (PMID 24509483, 2014). "Compared to the staining intensities for RBL2 and HP1γ, the signal was always found weaker in MLS tumor tissues and RB1 staining was also weaker in MLS tissues compared to reference tumor tissues of other entities." (PMID 25093008, 2014). "While the RB1 genotypes of tumorspheres match those of the primary tumor, adherent cultures have the germline RB1 genotype." (PMID 23826078, 2013). "Although numerous indirect evidences have suggested a role of pRb pathway in epidermal homeostasis and in skin carcinogenesis, the early lethality of Rb-null mice precluded the study of actual Rb1 functions in skin." (PMID 24381932, 2013). "We have analyzed CtIP/RBBP8 and RB1 presence on all tumor samples and correlated their expression levels with cancer prognosis markers." (PMID 24403251, 2013). "The retinoblastoma gene (Rb1), localized in chromosome 13q14.2, was the first tumor suppressor identified more than 25 years ago." (PMID 24381932, 2013). "The overall tumor free survival rate was similar between the genotypes with 95% of Rb1+/+ mice and 100% Rb1∆L/∆L mice succumbing to tumors." (PMID 23936539, 2013).
tumor (continued). "MRI is well suited for following head and neck tumors that correspond to the primary tumor types Rb1+/− mice develop." (PMID 23454836, 2013). "If eRapa acts in a similar manner to DR, we predicted that chronic eRapa treatment of Rb1+/− mice would also have minimal effects on tumor development, growth, progression and life span." (PMID 23454836, 2013). "The RB1 tumor suppressor negatively regulates the cell cycle and is inactivated in a wide range of human tumors." (PMID 24200043, 2013). "The hyperphosphorylation of RB inactivates its role as a tumor suppressor, and thus mutations that target either CCND1 or RB1 are thus important for proliferation in cancer." (PMID 23717195, 2013). "Other tumor suppressors, such as RB1 and WT1, were also activated in these cells, consistent with multiple tumor suppression pathways being activated following introduction of physiological Wnt/β-catenin signaling in HONE1 cells." (PMID 24073846, 2013). "We showed that pRb was heavily phosphorylated, hence inactivated, in many RB1-proficient TNBC tumor lines, and this correlated with high expression of Cyclin E1 in basal-A but not in basal-B tumors." (PMID 24265703, 2013). "Of note, the RB1 tumor suppressor gene coded at chromosome 13q14.2 was homozygous deleted together with the RCBTB2 gene in only one tumor (G97) from our series." (PMID 23029397, 2012). "The retinoblastoma gene (RB1) is the first tumour suppressor gene to be identified and it codes for a protein product, pRb, which has an important role in cell cycle during the G0-G1-S phase transition." (PMID 23304241, 2012). "Known tumor suppressor genes, e.g., CDKN2A (9p21.3), PTEN (10q23), and RB1 (13q14) were located within HD regions, as well as genes with potential tumor suppressor properties, e.g., CUL3 (2q36.2) and MGMT (10q26)." (PMID 22685613, 2012). "RB was one of the earliest childhood tumors to be characterized at the molecular level, with the discovery of the RB1 tumor susceptibility gene on chromosome 13 that exhibits tumor suppressor properties." (PMID 23233783, 2012). "Via IPA, RB1 and πK3R1 were associated with cell morphology, hematological system development and function; and PDGFBB and ERK1/2 were associated with tumor morphology, nervous system development and function, tissue morphology." (PMID 22616791, 2012). "Given its clinical relevance, the role of Rb1 during embryonic development and during tumor suppression has been studied intensely, mostly using mouse models." (PMID 23209449, 2012). "Studies using other neoplasias have also contributed to identify chromosomal regions that contain genes relevant for RB1 regulation." (PMID 23233862, 2012). "Given the different status of RB1 between tumor and normal cells, several studies have attempted to develop anti-tumor agents which selectively inhibit growth of tumors with dysfunctional RB1." (PMID 21447152, 2011). "E2F1 is a key transcriptional regulator of DNA replication and cell-cycleprogression, and is negatively regulated by the RB1 tumor suppressor." (PMID 21629784, 2011). "Similar chimera experiments with homozygous p107 deletion and heterozygous Rb1 deletion were performed to permit appreciation of the broader tumor spectrum, typical of humans heterozygous for Rb1 disruption." (PMID 21403899, 2011).
tumor (continued). "We report here that the CCND1/CDKN2A mRNA expression ratio predicts the RB1 status of cell lines in vitro and xenograft tumors and clinical tumor samples in vivo." (PMID 21447152, 2011). "On the other hand, PSDF 5 features copy number losses of the functional network module centered at RB1, a negative regulator of the cell cycle and a tumor suppressor." (PMID 22028636, 2011). "Among this cluster of adjacent genes is CDK4, a cyclin-dependent kinase that is an inhibitor of the RB1 tumor suppressor and known target of CDKN2A's p16 product." (PMID 21489305, 2011). "The CCND1/CDKN2A ratios of all the normal tissues were significantly higher compared with those of corresponding tumor tissues, indicating that the RB1 status of all the normal tissues was positive." (PMID 21447152, 2011). "The present study identified that the expression ratio of CCND1/CDKN2A predicts the status of RB1 in both cultured cancer cell lines and clinical tumor samples." (PMID 21447152, 2011). "Failed interactions between RB1 and NCAP-D3 in primary and tumor cells therefore result in loss of chromosome segregation fidelity, aneuploidy, micronuclei and anaphase bridges, all of which were observed in LmnaDhe/+ cells as well." (PMID 21464947, 2011). "Among tumor suppressor genes altered by copy-number losses, RB1 and WRN were also present in regions of recurrent copy-neutral LOH." (PMID 21151896, 2010). "Principal common CNAs were the well known MYC-associated gain and RB1/INTS6-associated loss that occurred in all mouse and human tumor groups, and the AURKA-associated gain occurred in BRCA2-related tumors from both species." (PMID 20735817, 2010). "After knocking out the tumor suppressor RB1 gene in the tumor-prone retinal cells, RB has to progress into full-fledged malignancy." (PMID 19190782, 2009). "The region 13q14 contains genes related to a variety of neoplasias, such as RB1, which however is located in a segment distant from the sequence analyzed." (PMID 21637642, 2009). "Here we report that LOH at the RB1 locus occurs at a high frequency in human basal-like and luminal B tumours, while occurring infrequently in luminal A and human epidermal growth factor receptor 2 (HER2)-enriched tumours." (PMID 18782450, 2008). "Therefore, the loss of RB1 function may also play a substantial role in the increased proliferation, possible resistance to hormonal therapies and poor prognosis that is seen in luminal B tumours." (PMID 18782450, 2008). "We next classified the tumours that were assayed for RB1 LOH analysis according to intrinsic subtype using the five-class single sample predictor." (PMID 18782450, 2008).
tumor (continued). "On average, RB1 was expressed at the lowest levels in basal-like tumours and at the highest levels in luminal A tumours, while the converse was observed for the average expression of a previously defined proliferation gene signature." (PMID 18782450, 2008). "While these experiments were performed with ER+ tumour cell lines, it does open the possibility that the RB1-defect in basal-like tumours plays a role in their increased chemosensitivity compared with most luminal tumours." (PMID 18782450, 2008). "This includes the most common genomic alteration, a deletion of 13q14.2–q14.3 including the RB1 tumor suppressor (∼60% of tumors)." (PMID 18784837, 2008). "Lastly, it has been demonstrated that the deletion of RB1 in the murine mammary gland is capable of initiating tumourigenesis and that many of these resulting tumours have basal-like features (E. Zacksenhaus, personal communication)." (PMID 18782450, 2008). "Similar findings concerning RB1 mRNA expression and the basal-like subtype have also recently been reported suggesting that this is a reproducible expression feature of basal-like tumours." (PMID 18782450, 2008). "RB1 protein expression also tended to be low in basal-like tumours, but this relationship was only near statistical significance (p = 0.064)." (PMID 18782450, 2008). "Strikingly, this experiment unequivocally demonstrated that from the 16 tumor suppressor genes that were scrutinized DNMT3b down-regulation caused specific loss of methylation at the promoters of APC, RAR-β, and Rb1 genes (Figure-3)." (PMID 18798999, 2008). "In the recent study by Bosco and colleagues, luminal tumour-derived cell lines were shown to be more proliferative and resistant to hormone therapy after knockdown of RB1, both of which are signatures of luminal B tumours." (PMID 18782450, 2008). "The loss of RB1 is also a well-characterised occurrence in many other human tumour types and it is probable that the p16INK4a-CDK4/6-RB pathway is disrupted in most human tumours." (PMID 18782450, 2008). "This analysis was able to sort the samples into two groups with the right most group containing most of the RB1 LOH positive tumours (21 of 27, 77.8%)." (PMID 18782450, 2008). "We found homozygous deletion (HD) to be a rare event in primary tumors and only found evidence of HD in two cell lines and one tumor on chromosome 13q14 where the retinoblastoma gene (RB-1) resides." (PMID 17925008, 2007). "Several genes including tumour suppressor genes and DNA repair genes such as hMLH1, RB1, VHL, p15, p16, RASSF1A, MGMT and BRCA1 in human cancers were shown to be epigenetically inactivated by DNA methylation in tumours." (PMID 14970867, 2004). "As several studies have pointed to cooperation between the CCND1 and RB1 genes, and to their joint involvement in the proliferative capacity of tumour cells, we also sought a possible link between CCND1 DNA and/or mRNA status and RB1 mRNA underexpression." (PMID 11870541, 2002).
tumor (continued). "Furthermore, the loss of cell cycle control through inactivation of tumor suppressor genes, particularly the RB transcriptional corepressor 1 (RB1), promotes uncontrolled proliferation and tumor progression." (PMID 40781861, 2025). "No NUDT15 loss were detected in the tumor cells of 23 RB1 expressed samples, whereas 14 out of 21 (66.7%) RB1‐loss samples exhibited co‐loss of NUDT15 in tumor cells with p = 3.9 × 10−6, supporting the frequent co‐loss of NUDT15 in CRPC patients with RB1 loss." (PMID 40904703, 2025). "If two RB1 mutations are identified in the tumor tissue alone but neither is found in the peripheral blood or saliva DNA, the case is most likely non-heritable, though mosaicism remains a possibility." (PMID 41009976, 2025). "Here we provide direct evidence of derivation of SCC of the thyroid from PTC, based on a unique combination of likely pathogenic mutations in KEAP1, STK11 (LKB1), and RB1 found in both tumor components, along with loss of one copy of chromosome 11 and additional somatic mutations in the SCC tumor." (PMID 40600748, 2025). "This limited efficacy stems from multiple resistance mechanisms: (a) EZH2-mediated epigenetic silencing of tumor suppressors (e.g., RB1) promotes chemoresistance, and (b) cancer stem cell populations maintain treatment-refractory properties through sustained Wnt/β-catenin pathway activation." (PMID 40746825, 2025). "These outcomes imply that tumor tissues can be acquired without enucleation from multiple patients, and that RB can be derived from RB1 mutation carriers who have never developed RB." (PMID 39422807, 2025). "In RB, a specific tumor suppressor RB1 functions to inhibit the development of the cancer." (PMID 41002743, 2025). "For instance, AURKA inhibitors, effective in RB1 and PTEN mutant tumours, could be trialed in tumours with mutations in less-studied tumour suppressors, such as FBXW7 and NSD1, for which we found AURKA to be a key gene in classification." (PMID 40775769, 2025). "Dasatinib may exert inhibitory effects on ARID1A‐deficient tumour cells by regulating the cell cycle regulatory network associated with cyclin—dependent kinase inhibitor 1A (CDKN1A) and RB1." (PMID 39779467, 2025). "As indirect evidence, CDK4/6 inhibitors can suppress RB1 expression, and antagonize the anti‐tumor effects of thiopurine (i.e., 6MP, azathioprine, and thioguanosine), which may be induced by coactivated NUDT15 expression." (PMID 40904703, 2025). "RB1 exerts its tumor suppressor function by binding to E2Fs in the nucleus." (PMID 39888288, 2025). "To date, this model provides the most comprehensive temporal analysis of tumor cells undergoing histological transformation and highlights key roles for Myc, Rb1 and the PI3K/Akt pathway in transformation, as these pathways are commonly altered in human T-SCLC." (PMID 39858043, 2025). "Some tumor suppressor genes, e.g., RB1 and CDKN1C, can be downregulated or inactivated in cancer via promoter hypermethylation or copy number loss, inactivating mutations in RB1 or imprinting allele switching of CDKN1C." (PMID 40414875, 2025).